CTLA4 (cytotoxic T-lymphocyte associated protein 4)
Diseases named in the same sentence as CTLA4 in open-access papers (continued):
Sharing a sentence is not in itself a finding about the gene and the disease.
tumor (continued). "In contrast, using a CT26 colon carcinoma model to evaluate the combinatorial therapy, only IL-21 and mAb CTLA-4 combination showed efficient results, five of eight mice presented complete regression of tumor with the IL-21 and mAb PD-1 combination having no antitumor effects in this model." (PMID 38638431, 2024). "Priming the tumour with the appropriate neoadjuvant chemoradiotherapy treatment could lead to higher immune infiltrations and higher expression of immune checkpoints, such as PD-1/PDL-1, CTLA4 or emerging new targets: LAG-3, TIM-3, TIGIT or ICOS." (PMID 38155973, 2023). "As this study provides proof-of-principle that Tregs impair anti-tumor immunity in the context neoadjuvant ICB, it will be crucial to identify how the variety of immunomodulatory drugs that are in clinical development will affect Treg activation beyond anti-PD-1 and anti-CTLA-4." (PMID 37089449, 2023). "Similar to other immune checkpoint proteins, such as cytotoxic T lymphocyte antigen 4 (CTLA-4) and program death-1 (PD-1), CD200 is thought to play a pro-tumorigenic role, via engagement of CD200R, in many tumor types primarily by suppressing anti-tumor T-cell and natural killer cell responses." (PMID 36738455, 2023). "In the neoadjuvant context of ICBs, tumor-specific CD8+ T cells isolated from non-major pathological response patients expressed high levels of genes associated with T cell dysfunction, such as TOX2, CTLA-4, TIM-3, and CD39." (PMID 37881432, 2023). "However, PD-1, TIGIT, and CTLA-4 are highly expressed in the TILs of TNBC patients, while PD-L1 and CD155 ligands are highly expressed in tumor cells or antigen presenting cells (APCs), which may make CD8+ T cells inefficient at killing tumor cells." (PMID 35770416, 2023). "However, CTLA-4 is activated in NSCLC and leads to immunosuppression and tumor immune evasion." (PMID 36895477, 2023). "While immune checkpoint inhibitors targeting the PD1/PDL1 and CTLA-4 axes have revolutionized cancer treatment, novel drugs are needed to overcome the limitations of current adaptive ICI-based immunotherapies, including insufficient tumor antigens and poor antigen presentation." (PMID 36831606, 2023). "The combination of anti-PD-1/CTLA-4 was shown to enhance T cell function, however without a sufficiently large number of activated dendritic cells to cross-present and activate the T cells, a sub-optimal anti-tumor effect was observed." (PMID 37449205, 2023). "Therefore, the effects of anti-CTLA-4 ICI and CRT-NPs on CRC tumor progression were analyzed as monotherapies, respectively, as well as in combination therapy to enhance the translatability of ICI use in patients, and potentially reduce their dose-dependent toxicities." (PMID 37376141, 2023). "We hypothesize that intrinsic expression of CTLA-4, PDCD1 (PD1), CD274 (PD-L1), PDCD1LG2 (PD-L2), CD276 (B7-H3), JAK2, and FoXO1 in neoplastic cells depends on BC immunophenotype, stem cell properties, and tumor microenvironment." (PMID 36901916, 2023). "Therefore, combination treatment with cetuximab plus anti-CTLA-4 antibody ipilimumab for HNSCC and this combination therapy after nivolumab administration for HPD may be expected to result in a higher tumor-control response." (PMID 37143088, 2023). "These initial successes support the general utility of the discovery process for pH-dependent mAbs, not just for immune-regulatory targets such as CTLA-4 and VISTA, but also for improving the on-target/off-tumor effects of targeting tumor-associated antigens on the cell surface of tumor cells." (PMID 37753969, 2023). "Finally, in conditions that were unresponsive to CpG + OX40 alone, the addition of anti-CTLA-4 restored the tumor curing ability of CpG + OX40 in A20-bearing mice, but not B78-bearing mice." (PMID 37016127, 2023). "Moreover, CTLA-4 expression on conventional CD4+(CD8−)CD25+FOXP3+ Tregs was substantially downregulated by SDT – by two-fold in both target and off-target tumours (large effect size for both)." (PMID 36319895, 2023).
tumor (continued). "Moreover, a significant relationship between CTLA-4 and BUB1B expression in HCC, suggesting that tumor immune evasion may influence the hepato-carcinogens that BUB1B mediates." (PMID 36829489, 2023). "CTLA-4 is a negative regulator of Treg cell homeostasis and their cell proliferation, and anti-CTLA-4 treatment in tumor models enhances the Treg cell population even though it yields tumor-specific immune responses, opposing their therapeutic outcomes in tumor studies." (PMID 37197667, 2023). "Our results support the hypothesis that acidity suppresses anti-tumour T lymphocyte function demonstrated by a significant upregulation of inhibitory immune checkpoints TIM-3, LAG-3, and CTLA-4 on the surface of OAC-derived T cells when cultured under low pH conditions ex vivo." (PMID 35708739, 2023). "Importantly, the tumor immune dysfunction and exclusion (TIDE) algorithm showed that in CCL2-high GBM group, the expression of CD274, CTLA4, HAVCR2 and other immune checkpoints were significantly increased, and the immune checkpoint blockade (ICB) therapy was accordingly more responsive." (PMID 38057698, 2023). "A tumor cell lysate vaccine administered in combination with anti-CTLA4 at 14 weeks of age failed to reduce prostate weight at 19 weeks of age, but the incidence of tumors (histologic invasive adenocarcinoma) was reduced from 69% in controls to 43% in the treatment group." (PMID 37372999, 2023). "Like CTLA-4 and PD-1, certain miRs, such as miR-146a, promote down-regulation of both innate and adaptive immune responses and may impact ICI-related survival, in part by counteracting cell escape mechanisms in the tumor microenvironment." (PMID 36900420, 2023). "A key aspect of tumor immune surveillance is that costimulatory or coinhibitory ligands, such as B7-1 or PD-L1, that interact with cognate costimulatory or coinhibitory receptors, such as CD28/CTLA-4 or PD-1, on T cells to elicit or suppress tumor-antigen-specific immune responses, respectively." (PMID 37662958, 2023). "Targeting two overexpressed receptors, for instance CTLA-4 and OX40, in the tumor has the potential to increase the localization of BsAbs to the tumor site compared to monospecific antibodies, which may reduce the risk of systemic T cell activation and improve efficacy." (PMID 37441075, 2023). "Interestingly, Belinostat, a HDAC inhibitor, improves the anti-tumor activity of anti-CTLA4 but not of anti-PD1 therapy in a murine hepatocellular carcinoma model." (PMID 37928272, 2023). "Anti-PD-L1 plus anti-CTLA-4 may also be a better option in patients with high lactate dehydrogenase, brain metastases, or mucosal melanoma, while anti-PD-1 plus anti-LAG-3 may be preferred in the elderly and perhaps patients with low tumour burden." (PMID 37507765, 2023). "As crucial immune checkpoint molecules, T-cell inhibitory receptors, including CTLA-4, PD-1, TIM-3, LAG-3, and TIGIT, are essential in limiting immunopathology and terminating effective immune response, while they can also inhibit effective anti-tumor immunity." (PMID 37056782, 2023). "We found CTLA-4-positive and -negative lymphocytes as well as positive tumor cells." (PMID 37415208, 2023). "All patients in this cohort received ICIs [either as single agent (PD-1 or CTLA4 inhibitors) or in combination (PD-1 and CTLA4 inhibitors)] and exhibited either primary or acquired resistance to therapy, and all were ICI refractory at the time of death and tumor sampling." (PMID 36977461, 2023). "Of note, in their model, they used both anti-CTLA-4 and anti-PD-1 inhibitors and found that the addition of either the class I specific HDAC inhibitor, entinostat, or DNMT inhibitor, azacitidine (5-AZA), significantly decreased metastases and tumor growth, and increased survival." (PMID 37120591, 2023). "Interestingly, although we did not observe an increase in PTGS2 expression in tumor tissue, there was a weak positive correlation between CTLA4 in normal tissues and HGSOC." (PMID 38201508, 2023).
tumor (continued). "The resulting tumour-immune dysfunction and exclusion (TIDE) score is one of the first multigene signatures that predicts the outcome of cancer patients treated with first-line anti-PD-1 or anti-CTLA-4, instead of using single biomarkers like PD-L1 or tumour mutation load." (PMID 37454231, 2023). "The results revealed that neither the immunotherapy cocktail nor Doxil monotherapy affected tumor growth, whereas a combination of the three components (PD-1 and CTLA-4 antibodies, Doxil nanomedicine, and tranilast) resulted in a significant reduction exceeding 50% compared to the untreated group." (PMID 37929901, 2023). "Since our analyses were conducted with heterogeneous tumor samples, absent correlations between CTLA4 methylation and protein expression might not necessarily exclude a potential biological connection." (PMID 37415208, 2023). "With the aim to investigate whether multiparametric CEST-MRI is able to assess early response to immune checkpoint blockade by detecting therapy-induced metabolic changes within the TME, 4T1 or 67NR tumor-bearing mice were treated with a combination therapy of anti-PD1 and anti-CTLA4." (PMID 37641066, 2023). "CTLA-4, TIGIT and KLRG1 may thus contribute to the reduced anti-tumor activity in aging mice." (PMID 37752597, 2023). "In the absence of CTLA-4 blockers, the inhibition of the PD-1/PD-L1 checkpoint would not lead to anti-tumor activity as T cells would have been inactivated in the priming phase, and since they have not yet reached the effector phase they would be absent from tumor tissues." (PMID 38069095, 2023). "Furthermore, KIF18A expression was positively correlated with many common immune checkpoints, including PD-L1, PD-1, CTLA4, TIGIT, HAVCR2, PDCD1LG2, and LAG3, indicating that KIF18A may be a new target for tumor immunotherapy." (PMID 36830695, 2023). "In NSCLC cells, anti‐CTLA-4 antibody was able to induce PD‐L1 expression and to promote NSCLC cell proliferation and tumor growth in the absence of adaptive immunity, suggesting that tumor cell‐intrinsic CTLA-4 can regulate PD‐L1 expression and cell proliferation in cancer cells." (PMID 37415208, 2023). "While checkpoint blockade using anti-CTLA-4 ipilimumab, and anti-PD1 antibodies nivolumab or pembrolizumab for DMG has failed as a monotherapy, enhancement of CAR T cell immunotherapy in combination with checkpoint blockade may improve anti-tumor efficacy." (PMID 37152812, 2023). "Since anti-CTLA-4 and anti-PD-L1 use non-redundant mechanisms and act at different time points in the anti-tumour immune response, dual immune checkpoint inhibition in combination with RT may be a future therapeutic option." (PMID 38259489, 2023). "In addition, another study showed that following melanoma-specific CD4+ T cell therapy combined with OX40 co-stimulation or anti-CTLA-4, complete tumour eradication was dependent on neutrophils killing of antigen-negative tumour cells." (PMID 37180120, 2023). "They found that MEK inhibitors not only had a direct killing effect on tumor cells, but also promoted tumor recognition by CD8+ T cells, increased the expression of cytokines such as IFN?, IL12, IL6 and TNFa, and prevented T cell depletion by downregulating PD-L1, CTLA-4, TIM-3 and LAG-3." (PMID 37016422, 2023). "Furthermore, tumor-infiltrated CD8+ T and CD4+ T cells in the allografts highly expressed the activation/exhaustion markers, such as GZMB, GZMK, PDCD1, LAG3, HAVCR2, and CTLA-4." (PMID 37980406, 2023). "Anti-CTLA4 alone had a small anti-tumor effect at 3 weeks but not at 5 weeks post-therapy." (PMID 37372999, 2023). "The relatively low overexpression of PD-L1 and CTLA-4 on the surface of 4T1 cells after PDT, and the high overexpression of CD80, raised the expectation that PDT-ICB combinations could improve the treatment outcome in this tumour model." (PMID 37468749, 2023).
tumor (continued). "Simultaneous PD-1/CTLA-4 inhibition and eosinophil depletion with or without DPP4i results in out-of-control tumor growth, which denotes the crucial role of eosinophils in controlling tumor volume even when T cells are activated." (PMID 37587450, 2023). "Therefore, additional strategies targeting TIGIT and/or CTLA-4 may enhance the strength and durability of CTL-mediated anti-tumor response of GBM to immunotherapy." (PMID 37731483, 2023). "We also found that PD1, PD-L1, CTLA-4 and PIK3CD in BRCA had a highly significant relationship, similar to what we found in the analysis of the TIMER data.Our findings show that PIK3CD-mediated tumorigenesis of BRCA may entail tumor immune evasion." (PMID 37861728, 2023). "Previous studies have shown that TAMs in HCC tumor stroma produce various proinflammatory cytokines, including TNF-α, IL-β, IL-6 and IL-23, which induce the expansion of CD4+ Th17 cells, according to the overexpression of PD-L1, CTLA4 to inhibit antitumor immunity." (PMID 37745297, 2023). "Moreover, tumor regression mediated by cytotoxic CD4+ T cells is dependent on MHC‐II‐restricted manner, which could be enhanced by anti‐CTLA‐4 antibody." (PMID 37829505, 2023). "Conversely, in other tumor models, CTLA-4 blockade alone was not effective." (PMID 36831435, 2023). "CTLA-4 suppresses T cell activity and inhibits immune responses by inhibiting the binding of the costimulatory molecules CD80 or CD86, found on the surface of antigen-presenting cells (APCs) in the tumor-draining lymph nodes (TDLNs), to the coactivation receptor CD28." (PMID 37221584, 2023). "In the absence of PD-L1, CTLA-4 immuno-expression in tumor cells and related adjuncts like s-CTLA-4 levels in serum may be studied so as to analyse whether they conform as biomarker for predicting responsiveness to ICPIs." (PMID 36879122, 2023). "Future therapies to overcome the inhibitory immune checkpoints beyond CTLA-4 and PD-1/PD-L1, such as therapies targeting LAG-3, TIM-3 and TIGIT, may be clinically beneficial since immune exhaustion and subsequent tumor escape remains critical for RCC progression." (PMID 37173966, 2023). "Anti-CTLA-4 and RFA in the B16-OVA model have been shown to augment the anti-tumor effect of splenocytes, which resulted in long-lasting tumor protection and regulatory T cell depletion in addition to increased tumor-specific T cell numbers, therefore protecting mice from tumor challenges." (PMID 37251920, 2023). "In an A20 tumor mouse model, the systemically administrated engineered bacteria were able to home to, and engraft in, tumors and be reliably and chronically activated by a brief non-invasive FUS treatment to release anti-CTLA-4 and anti-PD-L1 and significantly suppress tumor growth." (PMID 37180717, 2023). "To compare ALPN-202 to dual PD-1 and CTLA-4 checkpoint blockade in an in vitro setting, we co-cultured primary human E6 TCR transgenic T cells (human papilloma virus (HPV) E6 peptide-specific) with autologous M2c macrophages and PD-L1-expressing SCC152 human tumor cells at a 1:1:1 ratio." (PMID 35379805, 2022). "Furthermore, we highlighted that anti CTLA-4 + anti PD-1 maintained its efficacy in late-intermediate tumor (d12) but not in advanced tumors (d14)." (PMID 36685577, 2022). "Meanwhile, the combination of anti-CTLA-4 and anti-PD-1 antibodies relieved the immunosuppression of the GBM TME by promoting the secretion of cytokines like IL-1β, IL-2, IL-12, and TNF-α, which increased the proportion of M1 polarized TAMs and enhanced the immunosurveillance at the tumor site." (PMID 36311702, 2022). "Splenocytes from tumor free mice treated with anti-PD1 + anti-CTLA4, anti-PD1 + anti-CTLA4 + PRO, and anti-CTLA4 + PRO harbored higher number of tumor reactive T cells with a memory phenotype against MCA205 cancer cells, compared to splenocytes from tumor naïve mice." (PMID 35017664, 2022).
tumor (continued). "Results revealed that GLUT1 expression positively correlated with PD-L1 (P value=1.59e-02) and negatively correlated with PD-1 (P value=1.36e-02) in PAAD, and no significance was observed between GLUT1 expression and CTLA-4 expression after adjustment for tumor purity." (PMID 35711842, 2022). "For example, high levels of Treg-intrinsic CTLA-4 may aid in suppressing dendritic cells’ activities by affecting CD80 and CD86 expression; while CD25 expression may impact effector T cell and NK cell responses by quenching IL-2 in tumour microenvironment." (PMID 35493450, 2022). "Moreover, the combination therapy of targeting CTLA-4 and PDCD1 could better suppress tumor progression." (PMID 36428756, 2022). "Perhaps indicative of the modest effect of LAG-3 blockade as a monotherapy in human cancers and mouse tumour models complete knockout of LAG-3 in mice displayed normal immune function – in stark contrast to the lymphoproliferative disease observed in CTLA-4 knockout mice." (PMID 35265944, 2022). "For clinical aspect, the prognostic model of APA-related lncRNAs was suitable for samples of different pathological types and could be used to evaluate the expression of immune suppression factors such as CTLA4, PD-1, and IL1, thus predicting the immune suppression of tumor tissues." (PMID 39279987, 2022). "In addition, researchers have also found that anti-PD-1 mainly improves the effector T cell function in the tumor microenvironment, while anti-CTLA-4 mainly inhibits the T cell activation in peripheral lymph nodes and PD-1/PD-L1 and CTLA-4 act on T cells in different stages of cellular activation." (PMID 35159131, 2022). "Besides the inherent limitations of the TIDE analysis, one possible explanation would likely be that the T cell dysfunction with multiple alternative immune checkpoints including CTLA-4 and LAG3 within the tumor microenvironment is beyond the salvage of the single-target immune checkpoint inhibitor." (PMID 36092894, 2022). "Unequivocal CTLA-4 immunostaining of tumor cells was not seen in our patients." (PMID 35091676, 2022). "The first-line use of dual ICIs may be supported by the frequent expression of CTLA4 in PitNETs, regardless of tumor type, but this point was not addressed in refractory PitNETs." (PMID 36077631, 2022). "While the tumor antigen presentation was shown to be improved by immunogenic tumor cell death (ICD) inducers (mainly chemotherapeutic agents), the sustained CD8 T-cell activity can be triggered by immune checkpoint blockers (ICBs: anti-PD-1/PD-L1 and anti-CTLA-4 Ab)." (PMID 36429101, 2022). "1,25(OH)2D3 upregulates PDL1 and PDL2 and CTLA4 by direct transcriptional induction through the VDR and VDRE It has been suggested that elevated vitamin D3 signalling in humans could suppress anti‐tumour immunity via increased PDL1 expression." (PMID 35445563, 2022). "We deduced that it may be possible to reverse T cell dysfunction by intervention in these pathways to revive CD8+ T cells against tumor activity (such as TIGIT, TNFRSF9, CTLA-4, LAG3, PD-1), and this approach maybe represented new strategies for immunotherapy against LUAD." (PMID 36483553, 2022). "CTLA4+ TAMs are systemically expanded in mouse and human CRC metastatic settings, and facilitate tumor progression and metastasis directly by generating lipid droplets in tumor cells, and also indirectly by inducing immune exhaustion, leading to anti-PD1 resistance." (PMID 36211375, 2022). "Although antibodies targeting CTLA-4 and PD-1/PD-L1 represent a major breakthrough in cancer immunotherapy, application of checkpoint inhibitors in certain tumors have not led to significant tumor regression." (PMID 35720289, 2022). "Indeed, studies on different components of the tumor microenvironment led to the development of several targeted treatments, such as anti-VEGF, anti-EGFR, or, more recently, anti-PD-1, PD-L1, or CTLA4 antibodies, that considerably improved the prognosis of cancer patients." (PMID 35884357, 2022).